ZFAS1 (ZNFX1 antisense RNA 1)
Diseases named in the same sentence as ZFAS1 in open-access papers (continued):
Sharing a sentence is not in itself a finding about the gene and the disease.
breast carcinoma (continued). "In this study, we also showed ZFAS1 may have functions related to protein translation which has been previously reported for breast cancer." (PMID 29416676, 2018). "ZFAS1 was originally identified a regulator of alveolar development and epithelial cell differentiation in the mammary gland, subsequently studies showed ZFAS1 was aberrantly down-regulated in breast cancer tissues and cells." (PMID 30186041, 2018). "It reported that downregulation of ZFAS1 expression could promote cell proliferation, suggesting ZFAS1 as a putative tumor suppressor gene in breast cancer." (PMID 28977885, 2017). "Therefore, ZFAS1 expression in a variety of tumors was up-regulated and significantly correlated with poor prognosis, except in breast cancer." (PMID 28938617, 2017). "When compared to two studies focused on ZFAS1 in breast cancer, we reached contradictory data." (PMID 26506418, 2016). "The possible subtle differences between ZFAS1 expression in certain subtypes of breast cancer and normal cells could reflect the large number of samples examined, and thus be of minimal clinical impact." (PMID 27871336, 2016). "Among them, ZFAS1, which is the interest of this article, was first discovered in breast cancer (BC)." (PMID 40109869, 2025). "Taken together with the effects of ZFAS1 knockdown on mammary epithelial cell proliferation and differentiation, their results suggest ZFAS1 as a novel human tumor suppressor gene in breast cancer and that its dysregulation may be useful as a marker for breast cancer." (PMID 36406273, 2022). "Thus, Zfas1 is a novel and potential suppressor of breast cancer." (PMID 34123857, 2021). "Furthermore, knockdown of lncRNA ZFAS1 could inhibit breast cancer cell proliferation and metabolic activity, which indicated lncRNA ZFAS1 a tumour suppressor." (PMID 31565837, 2019). "According to the present studies that ZFAS1 was a regulator of alveolar development and epithelial cell differentiation in the mammary gland, we speculated that downregulated ZFAS1 may inhibit breast alveolar development and epithelial cell differentiation, and lead to breast cancer." (PMID 30186041, 2018). "In contrast, ZFAS1 is downregulated in breast cancer, which may function as tumor suppressor gene." (PMID 30186041, 2018). "The expression of ZFAS1, like GAS5, is also up-regulated in normal mammary glands compared to breast cancer tissues." (PMID 29416676, 2018). "Since cellular location will dictate function of lncRNA, cellular fractionation was performed to identify the subcellular localisation of ZFAS1 in MDA-MB-468 and MDA-MB-231 breast cancer cells." (PMID 27871336, 2016). "Expression of ZFAS1 and ZNFX1 has been evaluated in breast epithelial and breast cancer cell lines using these new sets of primers showing nearly identical patterns of expression." (PMID 27871336, 2016). "On the contrary, Hansji et al37 showed that ZFAS1 expression was not significantly different in breast cancer tissues from normal tissues according to RNAseq data set (HiSeqV2‐2015‐02‐24) from TCGA." (PMID 30288832, 2019). "However, ZFAS1 expression was significantly downregulated in basal and HER2 breast cancer subtypes compared to normal breast tissue." (PMID 30288832, 2019). "ZFAS1 is a lncRNA transcribed antisense to the ZNFX1 protein-coding gene, first identified as an lncRNA involved in mammary development and subsequently found to have altered expression in breast cancer." (PMID 29701689, 2018). "In this study ZFAS1 was negative or weakly expressed among all groups of samples indicating there is no significance of ZFAS1 in breast cancer." (PMID 26506418, 2016). "These transcripts for ribosomal proteins, like ZFAS1, do not exhibit appreciable differences in expression between human breast cancer and normal breast tissue samples." (PMID 27871336, 2016).
breast carcinoma (continued). "Analysis of TCGA data indicated that ZFAS1 expression was not reduced in breast cancers in general, but suggested that particular subtypes (basal, HER2-positive) show reduced expression." (PMID 27871336, 2016). "The expression of ZFAS1 was not significantly different in breast cancer patients as compared to healthy controls (P = 0.4941), which was the case also with RPS3 (P = 0.14)." (PMID 27871336, 2016). "Another non-protein-coding snoRNA host-gene, ZFAS1, which is highly expressed in the human mammary gland, was found to be down-regulated in breast cancer." (PMID 23991050, 2013).
glioma (28 papers, 2017 to 2025). A benign or malignant brain and spinal cord tumor that arises from glial cells (astrocytes, oligodendrocytes, ependymal cells). "High expression of ZFAS1 was closely associated with worse disease-free survival for PCa or gliomas patients." (PMID 36514044, 2022). "Consistent with our study, lncRNA ZFAS1 was associated with poor prognosis and up-regulated in glioma." (PMID 31775815, 2019). "Moreover, high ZFAS1 expression was associated with poor prognosis among patients with glioma." (PMID 36545127, 2022). "Further, ZFAS1 was shown to be m6 A methylated in glioma stem cells NCH421k, which drives gliomagenesis." (PMID 40382536, 2025). "ZFAS1 was also more highly expressed in glioma tissues and cells than in normal brain tissues and normal astrocyte HA cells." (PMID 36545127, 2022). "Downregulation of ZFAS1 or upregulation of miR-1271-5p was found to inhibit the progression of glioma by enhancing the apoptosis and inhibiting the repressing proliferation, migration, and invasion of glioma cells." (PMID 36545127, 2022). "Some, SOX2-OT, ZFAS1, SAMMSON, CASC19/PCAT2, and PVT1, have already been associated with various cancers, including gliomas." (PMID 35852875, 2022). "Inhibition of ZFAS1 significantly suppresses proliferation, migration, and invasion of glioma cells." (PMID 33980320, 2021). "ZFAS1 induces glioma progression by sponging miR‐150‐5p to regulate proteolipid protein 2 (PLP2), which is known as the functional target of miR‐150‐5p." (PMID 33980320, 2021). "LncRNA ZFAS1 serves as an unfavorable prognostic marker and can aggravate glioma progression through activating EMT and Notch signaling pathway." (PMID 33191397, 2020). "A study showed that the inhibition of lncRNA ZFAS1 suppressed glioma cells proliferation, migration and invasion in vitro." (PMID 31775815, 2019). "ZFAS1 expression was markedly overexpressed in glioma tissues and cell lines in reports by Gao et al30 and Lv et al31 with high ZFAS1 expression in glioma tissues being closely associated with advanced clinical stage and poor overall survival." (PMID 30288832, 2019). "Both univariate and multivariable Cox regression analysis revealed that upregulated ZFAS1 and the clinical stage were independent prognostic factors in the overall survival of glioma patients." (PMID 30288832, 2019). "Then, knockdown of ZFAS1 in glioma cell lines significantly suppressed proliferation, migration and invasion." (PMID 30186041, 2018). "The expression of ZFAS1 has also been reported to be high, and correlates significantly with poor prognosis in glioma tissues and cells." (PMID 28938617, 2017). "Among differentially expressed lncRNAs, we further validated seven lncRNAs (7SL, EGO-A, HOTAIR, JPX, MEG3, RNCR3, and ZFAS1) on a bigger cohort of glioma samples of different WHO malignancy grades and histopathological subtypes." (PMID 29138748, 2017). "Furthermore, ZFAS1 knockdown reduces the viability of glioma cells and increases their cisplatin chemosensitivity by targeting miR-432-5p." (PMID 33980320, 2021). "Thus, ZFAS1 exhibits an oncogenic role in glioma progression by regulating the EMT and the Notch signaling pathway." (PMID 33980320, 2021). "Moreover, the EMT and the Notch signaling pathway are inactivated in the glioma cells after ZFAS1 knockdown." (PMID 33980320, 2021). "Silencing of ZFAS1 could suppress cell proliferation by arresting the cell cycle and inducing cell apoptosis in glioma." (PMID 30288832, 2019). "Then they found knockdown of ZFAS1 in glioma cell lines could promote apoptosis, and inhibit cell proliferation, migration, and invasion." (PMID 30186041, 2018). "Taken together, these data showed ZFAS1 might act as a valuable prognostic biomarker and potential therapeutic target for glioma." (PMID 30186041, 2018). "In glioma patients, ZFAS1 overexpression was obviously correlated with advanced tumor grade." (PMID 29678899, 2018).
glioma (continued). "EMT and Notch signaling pathways in glioma cells were inactivated after ZFAS1 knockdown." (PMID 28938617, 2017). "In addition, in vitro experiments demonstrated that ZFAS1 knockdown in glioma cells inhibited the proliferation and invasion of glioma cells." (PMID 28938617, 2017). "Knockdown of ZFAS1 by upregulating miR‐432‐5p could enhance cisplatin cytotoxicity in glioma." (PMID 34178658, 2021). "Furthermore, knockdown ZFAS1 inhibited cell migration and invasion in glioma." (PMID 30288832, 2019). "Furthermore, ZFAS1 silencing could result in cell cycle arrest at the G0/G1 phase in glioma cell lines." (PMID 30186041, 2018). "For instance, lncRNA ZFAS1 suppresses miR‐1271‐5p, leading to HK2 upregulation and glioma progression." (PMID 38827027, 2024). "Recently, studies indicated consistent results about the relationship between high ZFAS1 expression and poorer prognosis in CRC, GC, HCC, glioma, melanoma and NSCLC." (PMID 29137442, 2017). "ZFAS1 also facilitated the progression of glioma by activating Notch pathway." (PMID 32744323, 2020). "Additionally, ZFAS1 could exhibit a tumor oncogenic role by regulating EMT and Notch signaling pathway in glioma and it facilitated ovarian cancer cell malignancy by participating in miR-150-5p/Sp1 axis." (PMID 28977885, 2017). "Furthermore, silenced ZFAS1 could impair migration and invasion by inhibiting the epithelial–mesenchymal transition through reducing the expression of MMP2, MMP9, N-cadherin, Integrin β1, ZEB1, Twist, and Snail as well as increasing E-cadherin level in glioma." (PMID 29245995, 2017).
myocardial infarction (20 papers, 2019 to 2025). Gross necrosis of the myocardium, as a result of interruption of the blood supply to the area, as in coronary thrombosis. "LncRNA zinc finger antisense 1 (ZFAS1) was shown to be an independent predictor of myocardial infarction and to accelerate cardiomyocyte apoptosis in myocardial infarction in mice caused by calcium overload." (PMID 37759491, 2023). "Several lines of data have revealed that lncRNAs interact with these key Ca2+ regulators, such as zinc finger antisense 1 (ZFAS1), myocardial infarction (MI) associated transcript (Miat), and zinc finger protein 593 antisense RNA (ZNF593-AS)." (PMID 35990951, 2022). "Previous study indicated that ZFAS1 could regulate cardiovascular system, and it is a potential diagnostic marker of acute myocardial infarction." (PMID 33952724, 2021). "The results indicate that EVs have the potential to reduce damage caused by myocardial infarction (MI) by inhibiting the expression of ZFAS1 and promoting the Akt/Nrf2/HO-1 pathway." (PMID 38915448, 2024). "Zinc finger antisense 1 (ZFAS1) is a novel lncRNA related to the development of multiple diseases including pulmonary fibrosis, myocardial infarction, and atherosclerosis." (PMID 38464828, 2024). "Mechanistically, myocardial infarction induces the expression of ZFAS1, which is controlled by the nuclear factor of activated T-cells C2 (NFATc2)." (PMID 35990951, 2022). "Another study found that ZFAS1 activated the mitochondrial apoptosis pathway in the mouse model of myocardial infarction." (PMID 33884101, 2021). "Knockdown of endogenous ZFAS1 improved cardiac function as the ejection fraction (EF), and fractional shortening (FS) resumed to almost normal levels in the mouse model of myocardial infarction." (PMID 33884101, 2021). "The expression of miR-150 was also reported to be dramatically upregulated in the myocardium remote zone, and the ZFAS1-miR-150 axis plays an important role in acute myocardial infarction-induced cardiomyocytes apoptosis." (PMID 31235686, 2019). "The reversible nature of the effect of ZFAS1 was observed following the knockdown, suggesting that targeting ZFAS1 with anti-ZFAS1 agents could serve as a novel therapeutic approach to safeguard cardiomyocytes from apoptosis generated by myocardial infarction." (PMID 38250803, 2023). "However, a series of studies on ZFAS1 in acute myocardial infarction (AMI) has shown that ZFAS1 is significantly differentially expressed between AMI patients and healthy people." (PMID 34604208, 2021). "In addition, studies have reported that ZFAS1 may play an emerging regulatory role in a variety of diseases, such as acute myocardial infarction, rheumatoid arthritis and cancer." (PMID 36855431, 2023). "lncRNA ZFAS1 facilitates intracellular Ca2+ overload and contractile dysfunction in myocardial infarction (MI) mouse models." (PMID 35571613, 2022). "Curiously, the lncRNA ZFAS1 was shown to promote intracellular Ca2+ overload and contractile dysfunction in a mouse model of myocardial infarction (MI) through direct interaction and inhibition of SERCA2a activity." (PMID 34850602, 2022). "Therefore, Knockdown of ZFAS1 could improve the cardiac function of myocardial infarction rats via regulating Wnt/β-catenin signaling pathway." (PMID 33952724, 2021). "ZFAS1 lncRNA is markedly upregulated in both mouse and human cardiac tissues subjected to myocardial infarction (MI)." (PMID 32117954, 2019). "Studies have shown that specific lncRNAs, such as ZFAS1 and CDR1AS, exhibit complementary changes following acute myocardial infarction, suggesting that these lncRNAs play important regulatory roles in cardiomyocyte injury and repair." (PMID 39135912, 2024). "Previously, we have identified ZFAS1 as a potential new long non-coding RNA (lncRNA) biomarker of acute myocardial infarction (MI) and as a sarcoplasmic reticulum Ca2+-ATPase 2a (SERCA2a) inhibitor, causing intracellular Ca2+ overload and contractile dysfunction in a mouse model of MI." (PMID 31819041, 2019).
myocardial infarction (continued). "The studies suggest that the inhibition of ZFAS1 and activation of the Akt/Nrf2/Heme oxygenase-1 pathway by MSC-derived EVs could potentially improve myocardial infarction outcomes." (PMID 37759491, 2023).
ovarian carcinoma (19 papers, 2017 to 2025). A malignant neoplasm originating from the surface ovarian epithelium. "MEG3, SNHG16, MNX1-AS1, and ZFAS1 are confirmed to be associated with ovarian cancer in the Lnc2cancer database, and their PMIDs are 28175963, 29461589, 29271994, and 28154416, respectively." (PMID 33980147, 2021). "The functional analysis shows that ZFAS1 is implicated in ovarian cancer tumorigenesis via the positive regulation of protein-coding genes that affect translational and ribosome processes." (PMID 28154416, 2017). "LncRNA zinc finger antisense 1 (ZFAS1) that has been shown to participate in the development and progression of several cancers was also found overexpressed in ovarian cancer tissues and associated with poor prognosis, by enhancing cell proliferation, migration, and invasion." (PMID 34204094, 2021). "In addition to the association of chemotherapeutic sensitivity in ovarian cancer, the associations between ZFAS1 and molecular subtypes were also studied." (PMID 28154416, 2017). "This study investigated the expression profiles of seven specific long noncoding RNAs (lncRNAs)—SNHG7, TUG1, XIST1, PRLB, TLR8-AS1, ZFAS1, and PVT1—associated with epithelial ovarian cancer and their relationship with drug resistance." (PMID 39992529, 2025). "A report by Xia et al34 showed that ZFAS1 was upregulated in epithelial ovarian cancer (EOC) tissues and cell lines." (PMID 30288832, 2019). "Then, they found ZFAS1 play a critical role in promoting the proliferation, migration, and chemoresistance of epithelial ovarian cancer cell lines." (PMID 30186041, 2018). "They further found ZFAS1 promoted proliferation, migration, and chemoresistance of epithelial ovarian cancer." (PMID 30186041, 2018). "We reported that long non-coding RNA ZFAS1 was upregulated in epithelial ovarian cancer tissues, and was negatively correlated to the overall survival rate of patients with epithelial ovarian cancer in this study." (PMID 28099946, 2017). "Inhibition of miR-150-5p rescued the suppressed proliferation and migration induced by depletion of ZFAS1 in epithelial ovarian cancer cells, at least in part." (PMID 28099946, 2017). "ZFAS1 promoted the increased expression of SP1 in ovarian cancer by competitive antagonism against miR-150 to enhance the ability of cell proliferation and chemotherapy resistance for ovarian cancer cells." (PMID 28938617, 2017). "Taken together, our findings revealed a critical role of ZFAS1/miR-150-5p/Sp1 axis in promoting proliferation rate, migration activity, and development of chemoresistance in epithelial ovarian cancer." (PMID 28099946, 2017). "We further found miR-150-5p was a potential target of ZFAS1, which was downregulated in epithelial ovarian cancer tissue." (PMID 28099946, 2017). "It was reported that ZFAS1 could regulate the expression of Sp1 in ovarian cancer cell malignancy by targeting miR-150-5p." (PMID 35112985, 2022). "Therefore, the ZFAS1/miR-150-5p/Sp1 axis is responsible, at least in part, for the regulation of cell malignancy and cisplatin and paclitaxel-resistance in ovarian cancer cells in vitro." (PMID 34204094, 2021). "Moreover, knockdown of ZFAS1 improved cisplatin and paclitaxel-sensitivity in ovarian cancer cells, indicating an additional role in chemoresistance." (PMID 34204094, 2021). "By searching related literature and databases, about 30% lncRNAs have been verified to play roles in the regulation of proliferation, invasion, and migration of ovarian cancer cells, including ZFAS1, SNHG1, GAS5, EMX20S, GIHCG, TP53TG1, EPB41L4A-AS1, SNHG8, SNHG6, and HCP5." (PMID 33519912, 2020). "In addition, the analogous clinical significance of ZFAS1 was also reported in esophageal squamous cell carcinoma and ovarian cancer." (PMID 29678899, 2018). "And ZFAS1/miR-150-5p may serve as novel markers and therapeutic targets of epithelial ovarian cancer." (PMID 28099946, 2017).
ovarian carcinoma (continued). "While depletion of ZFAS1 inhibited proliferation, migration, and development of chemoresistance, overexpression of ZFAS1 exhibited an even higher proliferation rate, migration activity, and chemoresistance in epithelial ovarian cancer cell lines." (PMID 28099946, 2017). "Several lncRNAs like ZFAS1, MALAT1, H19 have been shown to increase resistance to cisplatin while lncRNA like GAS5, NEAT1 lower cisplatin resistance in ovarian cancer cells." (PMID 39912983, 2025). "A prognostic signature with eleven lncRNAs, including NEAT1, HOTAIR, MALAT1, ANRIL, CCAT2, ZFAS1, UCA1 have been shown to predict poor patient survival and outcome in ovarian cancer patients." (PMID 39912983, 2025). "In vitro experiment results showed that the ZFAS1 expression level was upregulated in A2008, HeyA8, and HeyC2 cell lines treated with cisplatin compared with the control group, which indicates that cisplatin could increase the ZFAS1 expression level in ovarian cancer cells." (PMID 28154416, 2017). "To investigate the potential targets of ZFAS1, we used DIANA TOOLS and found the miR-150-5p was directly regulated by ZFAS1, which further promoted ovarian cancer progression by regulating Sp1." (PMID 28099946, 2017). "LncRNA ZFAS1 is overexpressed in epithelial ovarian cancer cells and directly targets miR-150-5p to enhance the expression of specificity protein 1 (SP1), which makes ovarian cancer cells resist to cisplatin and paclitaxel." (PMID 34660304, 2021).